GPER1 (G protein-coupled estrogen receptor 1)
Diseases named in the same sentence as GPER1 in open-access papers (continued):
Sharing a sentence is not in itself a finding about the gene and the disease.
endometrial cancer (66 papers, 2008 to 2025). Primary or metastatic malignant neoplasm involving the endometrium (mucous membrane that lines the endometrial cavity). "In contrast, in the majority of cancer entities including breast and endometrial cancer, GPER1 expression was significantly reduced and associated with the hypermethylation of the GPER1 gene promoter." (PMID 39796024, 2024). "GPER1 was found to be overexpressed in endometrial cancers where ER and PR were downregulated, and in high-risk endometrial cancers with lower survival rates." (PMID 32906618, 2020). "Prior research has also established the role of GPER1 in estrogen-related conditions, including female breast and ovarian malignancies, cervical and endometrial cancers, male prostate cancer, gastrointestinal tract cancers, and melanoma." (PMID 38666956, 2024). "This article provides a summary and update of the current findings on the role of ERβ, GPER1, and ERRs in ovarian and endometrial cancer." (PMID 37345182, 2023). "Study concerning endometrial cancer had found that GPER1 expression was reduced in endometrial cancer cell lines, which is consistent with our results." (PMID 37921845, 2023). "For this purpose, original research articles on the role of ERβ, GPER1, and ERRs in ovarian and endometrial cancers listed in the PubMed database have been reviewed." (PMID 37345182, 2023). "Tamoxifen acts as an estrogen agonist through GPER-1, which is more highly expressed in breast and endometrial cancer cells that show primary or secondary resistance to tamoxifen." (PMID 32906618, 2020). "The estrogen-agonistic effect of tamoxifen in endometrial cancers can also be explained by the expression of G-protein coupled estrogen receptor 1 (GPER-1), a membrane-bound estrogen receptor for which tamoxifen and other “antiestrogens” are pure agonists." (PMID 32906618, 2020). "The interaction of NLK with G protein coupled estrogen receptor 1 (GPER-1) contributes to cell growth by activating the PI3K signaling in endometrial cancer cells." (PMID 32547396, 2020). "Immunohistochemistry was performed to assess AMF and GPER-1 expression in endometrial cancer specimens and normal endometrium." (PMID 30836961, 2019). "Furthermore, a positive clinical correlation between AMF and GPER-1 was found in endometrial cancer." (PMID 30836961, 2019). "Furthermore, GPER1 agonists enhance tumor growth of endometrial cancer cell line xenografts." (PMID 39252786, 2024). "Similarly, it has been shown that exposure to the estrogen disruptor, 2,2′,4,4′-tetrabromo diphenyl ether-47 (BDE-47), attenuates the sensitivity of endometrial carcinoma cells to Cp, thus eliciting chemoresistance, at least in part via a GPER1 signaling pathway." (PMID 35955435, 2022). "In endometrial carcinomas, estrogen-induced LSD1 expression levels via G-protein-coupled estrogen receptor 1 (GPER)." (PMID 35563463, 2022). "Our study uncovers a novel mechanism that AMF directly binds to GPER-1, and subsequently activates PI3K signaling pathway, which in turn accelerates the endometrial cancer cells growth." (PMID 30836961, 2019). "Western blotting using anti GPER-1 C- and N- terminal antibodies detected GPER-1 in total protein extracts from isolated rat LC, human testis and Hec50 endometrial cancer cells." (PMID 24736568, 2014). "Thus, we provide the first piece of evidence that GPER-1 interacts with AMF and the complex contributes to endometrial cancer progression in animal and human histological experiments." (PMID 30836961, 2019). "Similarly, agonistic activity of tamoxifen increases the proliferation of endometrial cancer cells by activating the GPER-1/EGFR/ERK1/2/CyclinD1 route, data that is in agreement with the observation that endometrial cancer patients under tamoxifen treatment exhibit a worse prognosis." (PMID 33117280, 2020).
endometrial cancer (continued). "However, our results show that AMF may affect EC growth through GPER-1 both in the estrogen-dependent endometrial cancer cell line Ishikawa and the non-estrogen-dependent endometrial cancer cell line SPEC-2." (PMID 30836961, 2019).
breast tumor (51 papers, 2008 to 2026). "It has been shown that use of tamoxifen on patients with initial GPER-1 positive breast tumors increases GPER-1 protein expression and markedly reduces patient survival." (PMID 33117280, 2020). "Indeed, studies have indicated an increased expression of GPER1 in breast tumors with an acquired tamoxifen resistance." (PMID 33374170, 2020). "It has been shown that approximately 60% of all breast tumors are GPER-1-positive." (PMID 33117280, 2020). "Interestingly, E2 was also able to trigger a differential landscape of miRNAs in GPER1 positive and ER-negative CAFs derived from primary and metastatic breast tumors, suggesting a fine regulation of miRNA expression by GPER in very different cancer microenvironments." (PMID 33374170, 2020). "Three different receptors for estrogens have been identified in breast tumors, two nuclear receptors, ERα and ERβ, and a G-protein coupled estrogen receptor 1 (GPER) that initiates non-genomic effects of estrogens in the cytosol." (PMID 30687231, 2018). "Activation of GPER-1 by 4-OH tamoxifen also increases the expression of connective tissue growth factor (CTGF), which may be related to a more aggressive behavior of some breast tumors." (PMID 33117280, 2020). "Moreover, it has recently been reported that patients with GPER-1-positive breast tumors, after four to six months of treatment with tamoxifen, not only generated resistance to therapy, but also suffered an increase in the size of tumor mass." (PMID 33117280, 2020). "Also, ERβ or GPER1 activation opens L- and R-type voltage gated Ca2+ channels in hypothalamic neurons and GPER1 activation leads to IP3 generation in breast tumour cells, so although GPER effects may be Ca2+-dependent, the mechanism may be different in different cell types." (PMID 34746830, 2021).
prostate carcinoma (33 papers, 2013 to 2026). A carcinoma that arises from epithelial cells of the prostate gland. "The GPER1 SNP rs3808350 was associated with a higher risk of developing prostate cancer, especially in patients with a Gleason score ≥ 7 and with nodal and distant metastases." (PMID 42313278, 2026). "GPER1 expression was quantified by semi-quantitative RT-PCR using mRNA isolated from prostate cancer tissues and using benign prostate hyperplasia tissues as a control." (PMID 42313278, 2026). "In conclusion, the three ERs have distinct effects on prostate cancer, wherein ERβ and GPER1 exert tumor growth-suppressive effects, and ERα, ERβ2, and ERβ5 exert tumor growth-promoting effects." (PMID 36060947, 2022). "In prostate cancer, GPER1 has been demonstrated in Pc3 cells." (PMID 36233347, 2022). "The suppressed GPER1 function has been demonstrated to aid the growth of prostate cancer cells." (PMID 36060947, 2022). "Increasing evidence suggests a protective function for GPER1 in prostate cancer." (PMID 36060947, 2022). "Therefore, GPER1 is a pro-inflammatory mediator in castration-resistant prostate cancer involved in neutrophil movement, accumulation, adhesion, activation, and phagocytic respiratory burst." (PMID 33133022, 2020). "Besides, in the case of prostate cancer, GPER1 is known to control cancer cell growth through GPER1 mediated pathways." (PMID 31748686, 2019). "The significance of GPER1 expression and signaling in prostate cancer biology remains unclear." (PMID 36060947, 2022). "GPER1 acts as a tumor promoter in thyroid cancer, hepatocellular carcinoma, and renal cell adenocarcinoma, whereas GPER1 can inhibit the proliferation of lung cancer, prostate cancer, and estrogen receptor-negative breast cancer cells." (PMID 33425895, 2020). "Indeed, GPER1 was found to be an androgen-repressed gene and is therefore highly expressed in castration-resistant but not in androgen-responsive prostate cancer." (PMID 33133022, 2020).
Hypertension (32 papers, 2010 to 2025). The presence of chronic increased pressure in the systemic arterial system. "Lower serum levels of GPER-1 are associated with hypertension in postmenopausal women, but the relationship between GPER-1 and age-related ETB dysfunction is unclear." (PMID 35327604, 2022). "Only three of the 23 unique genes replicated, have been directly associated with hypertension (GPER1, PDE4B and TNFAIP3) so far." (PMID 35446883, 2022). "Together with the protective effect of the GPER agonist G-1 against LV dysfunction and remodeling following ischemia-reperfusion, hypertension, high-salt diet or loss of estrogen, these studies confirm the protective role of GPER1 in the heart." (PMID 34746830, 2021). "G-protein-coupled estrogen receptor (Gper1), a pro-hypertensive agent, has a similar effect that Gper1−/− rats exhibited significantly lower levels of Clostridiales beneath the phylum Firmicutes, implying that hypertension susceptibility genes act on gut microbes." (PMID 37215554, 2023). "Our lab has recently reviewed and outlined supporting evidence for GPER1 as a novel, therapeutic target for hypertension, especially in postmenopausal women." (PMID 36733911, 2023). "Between carvedilol and timolol there was an overlap of 15 genes, causing an upregulation, among others, of GPER1, PDE4B and TNFAIP3, which are genes directly associated with hypertension." (PMID 35446883, 2022). "In the current section, we will highlight the potential role of GPER1 in hypertension, cardiac and kidney diseases." (PMID 35327604, 2022). "Cardiovascular and kidney protection via GPER1 has been studied by the examination of angiotensin II-induced hypertension and oxidative stress in GPER1 knockout mice." (PMID 34089761, 2021). "G protein-coupled estrogen receptor-1 (GPER1) proteins modify their expression in the placenta of mothers with hypertension." (PMID 34867473, 2021). "Collectively, evidence suggests GPER1 is protective in hypertension, heart, and kidney disease." (PMID 35327604, 2022). "Although the exact molecular mechanism by which the deletion of Gper1 mitigates hypertension remains unclear, the researchers speculated that this process may be mediated by the gut microbiota." (PMID 36457803, 2022). "In the case of carvedilol, we showed that, beside genes with well-established association with hypertension (GPER1, PDE4B and TNFAIP3), the drug also affects genes that are only indirectly linked to hypertension due to their effects on artery walls or their role in lipid biosynthesis." (PMID 35446883, 2022). "Hypertension (HTN), pulmonary hypertension (PH), and atherosclerosis are typical vascular diseases, wherein ERα, ERβ, and GPER1 are known to mediate protective functions." (PMID 36060947, 2022).
Obesity (31 papers, 2013 to 2025). Accumulation of substantial excess body fat. "Together, these data demonstrate that activation of GPER1 alleviates estrogen deficiency–caused obesity, insulin resistance, hepatic lipid accumulation, and inflammation in female mice." (PMID 38246352, 2024). "Taken together, GPER1 protects against estrogen deficiency–induced obesity, insulin resistance, hepatic lipid accumulation, and inflammatory response in female mice." (PMID 38246352, 2024). "G protein–coupled estrogen receptor 1 (GPER1) is a membrane estrogen receptor involved in the development of metabolic diseases such as obesity and diabetes." (PMID 38246352, 2024). "Based on the findings that GPER1 acts a crucial role in the protective effects of estrogen on obesity, insulin resistance, hepatic lipid accumulation, and inflammatory response, we speculated that hepatic GPER1 may be involved in the progression of NAFLD." (PMID 38246352, 2024). "GPER1 has recently been postulated as a novel therapeutic target for treating obesity and comorbid metabolic dysfunctions on the basis of murine models showing that the selective GPER1 agonist G1 limited weight gain, reduced insulin resistance, and improved glucose and lipid homeostasis." (PMID 36835454, 2023).
triple-negative breast carcinoma (31 papers, 2012 to 2026). An invasive breast carcinoma which is negative for expression of estrogen receptor (ER), progesterone receptor (PR), and human epidermal growth factor receptor 2 (HER2). "For instance, AR suppresses GPER1 signaling to promote cell proliferation in triple-negative breast cancer." (PMID 39582864, 2024). "G protein-coupled estrogen receptor 1 (GPER1) is a potential therapeutic target for treating triple-negative breast cancers (TNBC)." (PMID 34768896, 2021). "Triple-negative breast cancer (TNBC) lacks estrogen receptor (ER) α, but the expression of estrogen receptors ERβ and G protein-coupled estrogen receptor 1 (GPER-1) is able to trigger estrogen-responsivity in TNBC." (PMID 33114740, 2020). "This suggests that cell surface-expressed GPER1 holds promise as a potential therapeutic target for non-triple-negative and triple-negative breast cancers." (PMID 37921845, 2023). "In an in vitro model, treatment with bisphenol, which can promote the migration, but not the proliferation of triple-negative breast cancer cells, has been found to activate YAP, and the inhibition of GPER1 attenuated the effects of BPS-induced YAP dephosphorylation." (PMID 33193095, 2020).
melanoma (30 papers, 2018 to 2025). A malignant, usually aggressive tumor composed of atypical, neoplastic melanocytes. "In our previous study, we found that GPER1 expression in pregnancy-related melanoma samples was associated with lower Breslow thickness, lower mitotic rate, lower hazard of local or distant metastases, and the protein expression was inversely associated with the presence of ulceration." (PMID 39252786, 2024). "Based on these observations, an ongoing phase I clinical trial has been initiated using pembrolizumab and a selective agonist of GPER1 for treatment of melanoma." (PMID 39252786, 2024). "Melanomas positive for both GPER1 and COL17 had significantly lower mean Breslow thickness and mitotic rate compared to cases positive for COL17 only." (PMID 39252786, 2024). "Mean H-score of GPER1 positive cases with Breslow thickness of more than 2 mm (H-score: 47.69) was significantly lower when compared with melanoma samples with Breslow thickness of 2 mm and less (H-score: 94.90) (p < 0.005)." (PMID 39252786, 2024). "GPER1 activation inhibits melanoma proliferation in both human and murine melanoma cell lines and induces c-Myc depletion, which is associated with reduced PD-L1 expression, potentially enhancing the response to immune checkpoint inhibitor therapies." (PMID 39252786, 2024). "In melanoma, the activation of GPER1 by its specific agonist G-1, inhibited the proliferation of mouse melanoma cell lines by decreasing cell division and blocking cell cycle progression in the G2 phase." (PMID 39252786, 2024). "Theoretically, while GPER1 expression decreases with increasing tumor size, COL17 expression emerges in high-risk, thicker melanomas, particularly at deeper invasive fronts." (PMID 39252786, 2024). "With regards to the different subtypes of melanoma, GPER1 protein was expressed in the majority of superficial spreading melanomas (SSM, n = 50/83, 60.20%), while it was only seen in one case out of the five nodular melanomas (NM)." (PMID 39252786, 2024). "GPER1 knockdown has been shown to negate the effects of G-1 and tamoxifen, indicating a GPER1-dependent pathway and suggesting that GPER1 activation exerts anti-proliferative effects in melanoma." (PMID 39252786, 2024). "The majority of thinner melanomas [Breslow thickness ≤2 mm (n = 40/57, 70.18%)] were positive for GPER1." (PMID 39252786, 2024). "Melanomas positive for both GPER1 and COL17 exhibited lower mean Breslow thickness and mitotic rates compared to cases positive for COL17 alone." (PMID 39252786, 2024). "It is clear that the role of GPER1 in melanoma needs further investigation, particularly in physiologically relevant mouse melanoma models." (PMID 35158973, 2022). "Systemic treatment with a GPER1 agonist combined with immune checkpoint blockade dramatically increased survival in melanoma-bearing mice, with up to 50% of the mice exhibiting tumor clearance." (PMID 36060947, 2022). "GPER1 expression was detected in over half of the melanoma samples (n = 54/94, 57.45%)." (PMID 39252786, 2024). "GPER1 shows inhibiting role and can be a treatment target in the melanoma." (PMID 36060947, 2022). "Furthermore, in this study, GPER1 signaling rendered melanoma cells more vulnerable to immunotherapy." (PMID 35158973, 2022). "GPER1 agonists inhibit melanoma cell proliferation, providing a protective effect against melanoma." (PMID 36060947, 2022). "GPER1 signaling enhances melanoma cell sensitization to immunotherapy." (PMID 36060947, 2022). "GPER1 controls melanin production and is expressed in melanoma cells of the skin." (PMID 36060947, 2022). "Further investigations with larger patient cohorts, supplemented by functional experiments, are necessary to corroborate our findings and elucidate the potential role of GPER1 and COL17 protein expression in melanoma." (PMID 39252786, 2024).
melanoma (continued). "In our retrospective study, we aimed to investigate the expression of GPER1 and the cell-residual endodomain of COL17 proteins in primary melanoma samples with known lymph node status in relation to the major clinicopathological factors." (PMID 39252786, 2024). "Our findings suggest that the immunohistochemical detection of GPER1 and COL17 proteins in melanoma may serve as valuable prognostic markers." (PMID 39252786, 2024). "The rationale for investigating both GPER1 and COL17 concurrently was to determine whether their co-expression shows any correlation with the major clinicopathological factors of melanoma." (PMID 39252786, 2024). "GPER1 positive melanoma samples had significantly lower Breslow thickness (p = 0.01) and mitotic rate (p = 0.007) when compared to GPER1 negative cases." (PMID 39252786, 2024). "In this retrospective study, we aimed to explore the expression patterns of GPER1 and the COL17 endodomain proteins in primary cutaneous melanoma tissue samples from patients with known sentinel lymph node status and correlated this with the common clinicopathological features of melanoma." (PMID 39252786, 2024). "The existing literature has reported on the expression of GPER1 and COL17 in various tumors, including melanoma, using immunohistochemistry and mRNA levels, yet without specific emphasis on lymph node metastatic status." (PMID 39252786, 2024).